MDM2 (MDM2 proto-oncogene)
Diseases named in the same sentence as MDM2 in open-access papers (continued):
Sharing a sentence is not in itself a finding about the gene and the disease.
sarcoma (continued). "Our results suggest that the co-overexpression of MDM2 and CDK4, along with multiple genetic factors, increases the tendency for high-grade sarcoma with a DDLPS-like morphology in transformed human BMSCs by accelerating their growth and migration and blocking their adipogenic potential." (PMID 31160689, 2019). "Protein levels of sarcoma cases with MDM2 amplifications are discriminable from those without, with a dissimilarity score of sdis = − 0.41 (p = 0.0; srand = − 8.9e−5)." (PMID 30442178, 2018). "However, we show that inhibitors of MDM2 and CDK4 antagonize each other in their cytotoxicity towards sarcoma cells." (PMID 30206211, 2018). "Given the co-amplification of the MDM2 and CDK4 genes in sarcoma, we sought to test whether the combined inhibition of both gene products might synergistically eliminate cancer cells." (PMID 30206211, 2018). "However, high levels of p16INK4a exist also in some tumors with wild type pRb as in those carrying HPV (E7 protein targets pRb), or that over express MDM2, commonly co-amplified with CDK4 in sarcomas." (PMID 26528855, 2015). "Patients with MDM2 positive group had better outcomes than MDM2 negative cases (p = 0.003, log‐rank), thus stressing the importance of accurately diagnosing these lesions and distinguishing them from undifferentiated sarcomas." (PMID 37395142, 2023). "Similarly, FISH for MDM2 was used to confirm the histological diagnosis of 23 WDLS, and MDM2 amplification was absent in 15 cases reclassified as undifferentiated sarcomas." (PMID 36164527, 2022). "Importantly, due to the lack of 12q13-15 amplification, pleomorphic sarcomas are not good candidates for targeted MDM2 inhibition." (PMID 36439412, 2022). "Among 15 patients with sarcoma who underwent 18F-FLT PET/CT, 5 patients (33%) patients were imaged at three time points: At baseline and at 1–15 weeks (MDM2-inhibitor treatment), and 10 patients (67%) were imaged twice: At baseline and at 1–4 weeks (MDM2 inhibitor, n = 5; c-met inhibitor n = 5)." (PMID 32106426, 2020). "Correlation analysis of CNVs from CCLE with drug-response data of CTRP in 27 sarcoma cell lines, 33 CNVs out of 63 genes correlated with either sensitivity or resistance to 17 chemotherapies from which actionable CNV signatures such as IGF1R, MYC, MAPK1, ATF1, and MDM2 were identified." (PMID 30704460, 2019). "Combination of the drugs at different concentrations in various MDM2-amplified sarcoma cell lines also revealed no synergism with regard to viability of cells (note that here viability was assayed immediately after 72 h of treatment, without allowing the cells to further proliferate)." (PMID 30206211, 2018).
sarcoma (continued). "However, Maleszewski et al6 argued that cardiac sarcomas harboring an MDM2 amplification should not be referred to as intimal sarcoma because these gene amplifications are nonspecific and also occur in other sarcomas including well differentiated /DDLPS and synovial sarcoma." (PMID 37395142, 2023). "Therefore, MDM2 inhibitor treatment alone may not induce apoptosis in this subset of sarcoma patients, and might instead result in transient cell cycle arrest." (PMID 35008180, 2021). "Since CD34 is a marker for lipomas and lipoma-like sarcomas, further analysis of SCL typically shows negative staining for desmin, RB1, MDM2, and SMA." (PMID 40980795, 2025). "It is well known that WDLPS and DDLPS present amplification of MDM2 and CDK4 genes on chromosome 12q13–15 as opposed to benign adipose tumors and other sarcoma subtypes." (PMID 25888631, 2015). "Furthermore, using total RNA, and not DNA samples, the fusion genes of various sarcomas could be identified, such as HMGA2-LPP and TLS-CHOP, while detecting MDM2 and CDK4 overexpression by quantitative real-time PCR." (PMID 24965044, 2014).
osteosarcoma (184 papers, 2000 to 2026). A usually aggressive malignant bone-forming mesenchymal neoplasm, predominantly affecting adolescents and young adults. "While MDM2, 2 SNP were only significantly associated with the risk of osteosarcoma in the sensitivity analysis." (PMID 38360742, 2024). "Is an H3-3A mutation or an MDM2 amplification detected in a conventional high-grade osteosarcoma, furthermore, sufficient to suggest a malignant giant cell tumor or a low-grade central osteosarcoma with high-grade transformation ?" (PMID 38231260, 2024). "The amplification of 12 chromosomes (12q13-15 region) which includes MDM2 gene is a potential hallmark of parosteal osteosarcoma, and well-differentiated and dedifferentiated liposarcoma." (PMID 35145371, 2022). "Additional molecular testing is helpful in differentiating desmoplastic fibroma from low-grade osteosarcoma (MDM2 amplification) and fibrous dysplasia (GNAS mutation)." (PMID 31838586, 2020). "Homozygous deletion of the CDKN2A locus, which is associated with poor prognosis in osteosarcoma, eradicates both expression of p16Ink4A and p14ARF, of which the latter is a negative regulator of MDM2." (PMID 31741049, 2020). "The Mdm2 protein is encoded by the Mdm2 oncogene, whose amplification has been frequently observed in soft tissue tumors, osteosarcomas and esophageal carcinomas." (PMID 27462439, 2016). "This osteosarcoma study noted that the MDM2-309 SNP was only associated with high-grade osteosarcoma in females." (PMID 21437228, 2011). "For example, gain of chromosome 8q23 and CDK4 alone or together with MDM2 is associated with poor prognosis in osteosarcoma." (PMID 17439659, 2007). "Additionally, one could imagine implementing an automatic detection of specific CNVs (such as MDM2 amplifications in low-grade osteosarcoma) to further enhance diagnostic accuracy." (PMID 35347251, 2022). "FISH analysis of a rare case of primary cardiac fibroblastic osteosarcoma revealed MDM2 gene amplification." (PMID 40904500, 2025). "Mdm2 also has been reported to be expressed in many tumors, especially soft-tissue sarcomas and osteosarcomas." (PMID 39911252, 2025).
osteosarcoma (continued). "Preclinical studies demonstrate that combining MDM2 inhibitors with adoptive NK cell therapy significantly suppresses osteosarcoma growth." (PMID 41323391, 2025). "Selective amplification of CDK4 and MDM2 is a particularly common phenomenon in low-grade osteosarcoma." (PMID 39322633, 2024). "In this study, we conducted high-resolution genomic and transcriptomic analyses on 33 samples from 25 osteosarcomas, encompassing both high- and low-grade cases with MDM2 and/or CDK4 amplification." (PMID 39322633, 2024). "Amplification of the MDM2 and CDK4 genes on chromosome 12 is commonly associated with low-grade osteosarcomas." (PMID 39322633, 2024). "Knockdown of the MDM2 gene inhibits the proliferation, migration, and invasion of osteosarcoma cells." (PMID 39062505, 2024). "In prior meta-analyses, associations of genetic polymorphisms in VEGF, MDM2, CTLA-4, TNF-a, TNF-b1, PRCKG, RECQL5, XRCC3, and GST with osteosarcoma susceptibility were investigated." (PMID 38360742, 2024). "In this study, we conducted comprehensive genomic and transcriptomic analyses on both high- and low-grade osteosarcomas exhibiting MDM2 and/or CDK4 amplification and verified our findings using longread whole-genome sequencing." (PMID 39322633, 2024). "The backbone of detected amplicons in MDM2-amplified osteosarcomas consists mostly of chromosome arm 12q sequences, likely arising from a chromothripsis event affecting chromosome 12." (PMID 39322633, 2024). "Supporting a possible biological significance is the fact that these events are recurrent, induce the expression of the 3′ partner genes, and cluster in MDM2-amplified osteosarcomas with either aggressive clinical behaviour or dedifferentiated morphology." (PMID 39322633, 2024). "RG7112 has been shown in vitro to have growth inhibitory and cytotoxic effects on MDM2 protein highly expressed SJSA-1 osteosarcoma cells." (PMID 38741108, 2024). "The outside facility found the biopsy to be MDM2 positive on stain, and the patient was diagnosed with a low-grade parosteal osteosarcoma." (PMID 38057715, 2023). "Endogenous GADD34 and MDM2 were knocked down by transfection with GADD34 siRNA and/or MDM2 siRNA in the human osteosarcoma cell line, U2OS, followed by culture for 2 weeks." (PMID 37228401, 2023).
osteosarcoma (continued). "Amplification of CDK4 and MDM2 was found in 67% of parosteal osteosarcoma that is a low-grade differentiated type of osteosarcoma and in 9–12% of classical osteosarcoma." (PMID 36611942, 2022). "The final diagnosis of two sarcomatous entities or liposarcomatous transdifferentiation of the parosteal osteosarcoma was only possible based on the detection of the MDM2-amplification in fluorescence-in-situ-hybridization." (PMID 35384584, 2022). "Overexpression of MDM2 was frequently observed in various types of cancers, such as osteosarcoma, rhabdomyosarcoma, and fibrosarcoma, and it was usually associated with poor prognosis." (PMID 35692096, 2022). "Low-grade osteosarcomas can transform into high-grade osteosarcomas and still preserve the amplification of chromosome 12q and overexpression of MDM2 and CDK4." (PMID 35049602, 2021). "Certain subsets of osteosarcoma harbor a supernumerary ring and/or giant marker chromosomes with amplification of the 12q13–15 region, including the murine double-minute type 2 (MDM2) and cyclin-dependent kinase 4 (CDK4) genes." (PMID 35049602, 2021). "Zhao et al67 also reported that circSAMD4A increased osteosarcoma growth by sponging miR‐1244 and thereby derepressing MDM2 expression." (PMID 33103338, 2021). "Circular RNA circSAMD4A contributes to osteosarcoma cell proliferation via targeting miR-1244/MDM2 expression." (PMID 34774083, 2021). "Case 7 presented with a conventional high‐grade osteosarcoma, however, the presence of low‐grade osteosarcoma components and the MDM2 and CDK4 immunoreactivity suggests that the patient had progressed from low‐grade osteosarcoma." (PMID 34008925, 2021). "MDM2 FISH analysis was feasible with an interpretable signal in 5 of the 24 investigated cases: 2 of 11 osteosarcoma cases, 2 of 7 ossifying fibroma cases, and 1 of 5 fibrous dysplasia cases." (PMID 35049602, 2021). "In cells with high basal levels of ribosomal biogenesis (e.g., NMNAT1 KO osteosarcoma cells), blocking rRNA synthesis (e.g., by ActD) leaves more ribosomal proteins unbound and able to interact with MDM2." (PMID 34445574, 2021). "In humans, MDM2 overexpression is common in many different tumor types, such as soft tissue tumor, osteosarcoma and esophageal cancer." (PMID 33173438, 2020). "In a recent study of 22 low-grade osteosarcomas (3 low-grade central, 14 classic parosteal, and 5 dedifferentiated parosteal osteosarcomas), an MDM2 (12q15) amplification was revealed in 100% of the cases by fluorescence in situ hybridization." (PMID 32295254, 2020).